RN7SL556P (RNA, 7SL, cytoplasmic 556, pseudogene)
Gene: Miscellaneous RNA gene on chromosome 7 (5,871,753 to 5,872,050, reverse strand). Ensembl gene ENSG00000277265.
Homologues: Orthologues: chimpanzee Metazoa_SRP (98% identical), macaque Metazoa_SRP (91% identical). Paralogues in human: RN7SL478P (97% identical), RN7SL1 (86% identical), RN7SL2 (86% identical), RN7SL3 (86% identical), RN7SL14P (82% identical), RN7SL296P (82% identical), RN7SL655P (82% identical), RN7SL660P (82% identical), RN7SL493P (82% identical), RN7SL220P (82% identical), RN7SL679P (82% identical), RN7SL126P (81% identical), and 705 more.